CRP (C-reactive protein)
Diseases named in the same sentence as CRP in open-access papers (continued):
Sharing a sentence is not in itself a finding about the gene and the disease.
colon carcinoma (86 papers, 2005 to 2026). "Elevated inflammatory markers, such as CRP and pro-inflammatory cytokines, are indicators of advanced stages of colon cancer and are associated with a poor prognosis." (PMID 39682667, 2024). "An association between high CRP levels and a right-sided colon cancer location was also observed, reaching significance in the U-CAN validation cohort." (PMID 39613865, 2024). "A case-control study nested within the Japan Public Health Center-based prospective study found a 1.6-fold increased risk of subsequent colon cancer for the highest versus the lowest quartile of CRP." (PMID 36407320, 2022). "By analyzing 172 CRC patients and 342 controls, a prospective nested case–control study found that the risk of colon cancer was higher in persons in the highest vs lowest quartile of CRP." (PMID 35715516, 2022). "A systematic review including 5 nested case-control and 3 cohort studies identified a positive but weak association between pre-diagnostic circulating CRP concentrations and colorectal and colon cancer risk." (PMID 36407320, 2022). "A nested case–control study conducted in Japan found that the highest quartile group of C-reactive protein was significantly associated with a subsequent risk of colon cancer compared with the lowest group." (PMID 35715516, 2022). "For example, a one-unit increase in CRP levels has been linked with a 2.29-fold increase in the risk of colon cancer." (PMID 34158611, 2021). "Accordingly, high values of CA-19.9, TNF-α, PCT, PTX-3, and CRP were found to pose a high risk for colon cancer." (PMID 33776564, 2021). "For cancer, genetically determined CRP was positively associated with tongue cancer, presenting a protective effect on colorectal and colon cancer." (PMID 34386016, 2021). "By contrast, a two-fold enrichment of mutant APC were observed in colon tumors with the concurrent CRP-286 SNP mutations (n = 38)." (PMID 25025473, 2014). "C-reactive protein remains significantly associated with a higher risk of colon cancer in ApcMin mice." (PMID 21188222, 2010). "Plasma CRP concentrations were higher among all colorectal cases combined compared with controls and the risk of colon cancer was higher in persons in the highest vs. lowest quartile of CRP." (PMID 15904534, 2005). "A question of interest is whether there is an association between physical activity via MET-hours/week and c-reactive protein, a biomarker of inflammation, with elevated levels of CRP associated with risk of developing colon cancer." (PMID 38773986, 2024). "The elevated level of CRP could be established as an important diagnostic biomarker marker for monitoring the development of colon cancer." (PMID 34096454, 2021). "Moreover, the same CRP variant rs1205 has been found to be associated with an increased risk of colon cancer in one study but with decreased risk in another." (PMID 32477370, 2020). "The practice of ST using elastic bands may have a public-health relevance for older women, since a prospective study suggested that an increase of 1.02 mg/L of CRP was correlated with 35% of increase risk to develop colon cancer." (PMID 28659812, 2017). "The role of anti-inflammatory medication, and thereby the reduction of CRP, in reducing cancer risk has been suggested in colon cancer, with a statistically significant difference in CRP seen between the absence and presence of colon cancer." (PMID 24794233, 2014). "In addition to cardiovascular disease and stroke, elevated CRP concentration was found to be associated with other diseases, such as diabetes, colon cancer." (PMID 23516433, 2013).
colon carcinoma (continued). "However, the risk factors identified are less suitable for the indication for surgery, since only preoperative risk parameters can be used and some of the preoperative risk factors (age, high CRP values) represent also risk factors for the presence of appendix malignancy." (PMID 36708422, 2023). "Therefore, preoperative plasma CRP concentrations may be an important risk biomarker for POD prediction in elderly patients with colon carcinoma after laparoscopic surgery." (PMID 29181397, 2017). "A study published in the British Journal of Surgery (BJS) reported that patients who underwent RAS had significantly lower C-reactive protein (CRP) levels on the first postoperative day than those who underwent LSS in colon cancer surgery." (PMID 39858025, 2025). "The maximum inhibition rates of CRP-1, CRP-2, CRP-3, and CRP-4 on colon cancer HCT-116 cells were 34.31 ± 0.83%, 36.65 ± 0.31%, 36.65 ± 0.31%, and 40.44 ± 1.44%, respectively, with CRP-4 showing the highest inhibition rate." (PMID 39195472, 2024). "The aim of this prospective study was to evaluate the prognostic significance of the C reactive protein-to-albumin ratio (CAR) in patients with colon cancer." (PMID 39064483, 2024). "In patients with colonic cancer with leakage, levels of high-sensitivity C-reactive protein (hs-CRP) were increased before surgery." (PMID 35652588, 2022). "The IL-6 produced in chronic inflammation has been shown to stimulate the CRP production in colon cancer cell lines." (PMID 34096454, 2021). "We observed that in subjects with breast and colon cancer, the CRP, PTX-3, and PCT levels were significantly and consistently higher than in the control group." (PMID 33776564, 2021). "The serum NF-κB, TNF-α, IL-6, PTX-3, PCT, and serum CRP concentration was significantly higher, and the serum sTRAIL concentration was significantly lower in the patients with breast and colon cancer than in healthy controls." (PMID 33776564, 2021). "Adaptive and innate immune markers in CRP-high and -low colon cancer patients according to MSI status." (PMID 34531864, 2021). "Colon cancer patients with high serum CRP and those with low albumin levels were significant more likely to suffer SSI occurrence (CRP: P < 0.05; Albumin: P < 0.01)." (PMID 31906993, 2020). "Chen and co-workers (2015), in 53 patients undergoing resection of colon cancer, reported a significant reduction on day 2 post-operative CRP with general plus epidural anaesthesia compared with general anaesthesia." (PMID 32348308, 2020). "Papadima and co-workers, in 40 patients receiving open surgery for colon cancer, reported a decrease of post-operative day 2 CRP in patients receiving general anaesthesia compared with epidural analgesia." (PMID 32348308, 2020). "The relationship between each anaesthetic technique and POD 2 CRP of patients undergoing elective open surgery for colon cancer." (PMID 32348308, 2020). "Among 525 colon cancer cases, patients with high CRP had poor prognosis, a result that was sustained within all disease stages when analyzed separately." (PMID 29929486, 2018). "This present study highlighted the predictive role of preoperative CRP concentrations for POD in elderly patients undergoing laparoscopic surgery for colon carcinoma." (PMID 29181397, 2017). "The univariate analysis and multiple logistic regression analysis suggested preoperative CRP concentrations as the only independent predicator for POD in patients undergoing laparoscopic surgery for colon carcinoma (OR: 5.87; 95% CI: 2.22–11.4; P = 0.018)." (PMID 29181397, 2017). "In conclusion, this present study highlighted the predictive role of preoperative CRP concentrations for POD in elderly patients undergoing laparoscopic surgery for colon carcinoma." (PMID 29181397, 2017).
colon carcinoma (continued). "We thus further examined 67 tumor/normal sample pairs of rectal cancer, which is very similar to colon cancer in both the cell type origin and genomic alterations showing high incidence of both APC and the CRP-286 SNP mutations." (PMID 25025473, 2014). "Serum levels of CEA, IL-8, VEGF, S100A11, C3adesArg, CD26, MCSF and CRP showed significant differences between colon cancer cases and controls (P < 0.05)." (PMID 22954206, 2012). "The analyses revealed combinations of CEA + IL-8 and CEA + CRP to show the best screening performance for colon cancer reaching a sensitivity of 47% and 39% in the validation set, respectively." (PMID 22954206, 2012). "The majority of patients were aged 65 years or more, had colonic tumours and had C-reactive protein concentration in the normal range (⩽10 mg l−1) prior to surgery." (PMID 16721360, 2006). "This is similar to the present findings for colon cancer cases, which the odds ratio of the highest serum CRP levels was 1.4 for colon cancer and 0.9 for rectal cancer, compared to the subjects with the lowest serum CRP levels." (PMID 16127232, 2005). "The depth of invasion influenced the CRP levels in dMMR colon cancer (p = 0.015)." (PMID 39857073, 2025). "T3 colon cancer patients had lower CRP levels than T4 CC patients (p = 0.028)." (PMID 39857073, 2025). "Given the lack of previous studies examining the association between RAS versus LAS, the inflammatory stress response (as indicated by CRP levels), and long-term survival in patients who underwent colon cancer surgery, an arbitrary CRP cutoff point was established for this analysis." (PMID 40383853, 2025). "C reactive protein and albumin serum levels are very accessible and cost-effective biomarkers, which may have prognostic utility for colon cancer patients." (PMID 39064483, 2024). "mCRP distribution in colon cancer patients stratified for serum CRP and MSI-status." (PMID 37006231, 2023). "Clinical characteristics of colon cancer patients according to the level of circulating CRP." (PMID 37006231, 2023). "CRP has been determined as a prognostic factor in nasopharyngeal carcinoma and colon cancer." (PMID 35928634, 2022). "In this study, we have demonstrated that circulating NF-κB, TNF-α, IL-6, PTX-3, PCT, and CRP levels in breast and colon cancer were significantly higher than in control groups and NF-κB levels were positively correlated with IL-6, PTX-3, PCT, and CRP in all patients." (PMID 33776564, 2021). "Patient and tumor characteristics in CRP high and -low colon cancer patients." (PMID 34531864, 2021). "In colon cancer, decreased expression of Nu-SIRT6 was associated with more frequent relapse in the subpopulation of patients with lymph node metastasis or higher levels of C-reactive protein." (PMID 30524965, 2018). "With these six variables introduced into the final multivariate analysis, the results suggested preoperative CRP concentrations as the independent predicator for POD in patients undergoing laparoscopic surgery for colon carcinoma (OR: 5.87; 95% CI: 2.22–11.4; P = 0.018)." (PMID 29181397, 2017). "Several meta-analyses have reported that inflammatory markers such as IL6 and CRP are associated with an increased risk of colon cancer but not of rectal cancer." (PMID 28051997, 2017). "Inflammation is also involved in the development of solid tumours such as colon cancer, as demonstrated by a prospective case-control study where the 172 subjects (out of 22,887 adults who were followed for 11 years) who developed colon cancer had higher plasma CRP." (PMID 28075340, 2017). "As expected, patients undergoing appendectomy showed a mean of preoperative CRP levels significantly higher than patients undergoing surgery for CD or for colon cancer (P<0.001), with notably higher inter-individual variation as shown by wide 95% confidence interval in the graph." (PMID 27551522, 2016).
colon carcinoma (continued). "ASA grade (HR 1.99, 95 % CI 1.28–3.10, p = 0.002), mGPS (HR 1.53, 95 % CI 1.11–2.10, p = 0.010), and breaching the established CRP threshold of 150 mg/L on POD 4 (HR 2.32, 95 % CI 1.29–4.20, p = 0.005) were independently associated with overall survival after surgery for colonic cancer." (PMID 27016295, 2016). "We have previously shown in a large EPIC cohort that high circulating C-reactive protein, a marker of systemic inflammation, was related to colon cancer risk in men, but not in women." (PMID 25884309, 2015). "Moreover, a statistical correlation between IL-8 with CRP is suggestive for the inflammatory component of colon cancer." (PMID 25408728, 2014). "Our novel multiplex biochip revealed combinations of CEA + IL-8 and CEA + CRP to show the best screening performance for colon cancer with 47% sensitivity, for early carcinomas with 33% sensitivity, and adenomas with 18% sensitivity at an overall specificity of 86%." (PMID 22954206, 2012). "In addition, the OR of the highest serum CRP levels was 1.42 (95% CI: 0.73-2.74) for colon cancer cases or 0.90 (95% CI: 0.30-2.30) for rectal cancer cases, compared to the lowest serum levels, but the difference was not significant." (PMID 16127232, 2005). "Higher serum CRP levels were not clearly associated with increased risk of colorectal or colon cancer." (PMID 16127232, 2005). "In addition, geometric mean serum CRP levels of colon cancer cases (0.49mg/L, ranges: 0.20-1.05 mg/L, n = 101) were nearly equal to those for controls (0.49 mg/L, ranges: 0.23-1.00 mg/L, n = 237)." (PMID 16127232, 2005). "Moreover, patients who received the BNT162b2 vaccine and have dMMR colon cancer had higher levels of CRP and sedimentation and lower levels of lymphocyte/CRP ratio, which suggest an inflammatory and immune relationship between mRNA-based vaccine and dMMR status." (PMID 38975417, 2024). "Additionally, Ramanathan and colleagues suggested that while an open surgery approach for colon cancer resection carries a greater inflammatory response than a laparoscopic approach, the predictive thresholds of CRP in post-operative complications were similar across both approaches." (PMID 38184537, 2024). "In addition, to the best of our knowledge, the C reactive protein-to-albumin ratio as a prognostic factor for colon cancer has previously been studied exclusively in Asian countries on a more heterogenous population, which included both colon and rectal cancer." (PMID 39064483, 2024). "Except for the N stage and KRAS status, the increased CRP-MCV was associated with males; older age (older than 60 years); presenting advanced T stage, M stage, and later TNM stage; accompanied by microsatellite instability; and right-sided and poorly differentiated colon cancer." (PMID 34221966, 2021). "The current study clearly demonstrated increased level of C reactive protein (CRP) in the serum of colon cancer patients and these studies are consistent with several lines of evidence of other studies that indicated the increased risk of colon cancer in patients with chronic inflammatory response." (PMID 34096454, 2021). "Multiple single nucleotide polymorphisms (SNP) have been identified which are associated with CRP levels, and Mendelian randomization studies have shown a positive association between SNPs increasing CRP expression and risk of colon cancer (but thus far not CVD)." (PMID 31622379, 2019). "Nonetheless, CRP is a nonspecific marker of inflammation, and additional studies of specific cytokines or factors that regulate acute-phase response are necessary to elucidate the mechanisms by which inflammation increases the risk of colon cancer." (PMID 21188222, 2010). "Preoperative inflammatory biomarkers, particularly CRP and NLR, offer important prognostic value for surgical decision-making and early postoperative outcomes in emergency colon cancer surgery." (PMID 42282231, 2026).
colon carcinoma (continued). "Conversely, UC complicated by colon cancer typically presented with onset in the 50s, elevated levels of ESR, C-reactive protein, and white blood cell count, as well as a pattern of total colon involvement." (PMID 41374953, 2025). "This nationwide cohort study examined a possible association between the surgically induced trauma expressed by the postoperative CRP response and long-term survival in patients undergoing RAS or LAS for UICC stage I–III colon cancer." (PMID 40383853, 2025). "The components of the bedside leak score (i.e., the preoperative albumin and the CRP on POD1 and POD3) are commonly used blood parameters in patient care after colon cancer surgeries." (PMID 37601530, 2023). "In the case of the results of colon cancer vs. control group patients, statistical significance was demonstrated for CEA and CRP (p < 0.001 in both cases)." (PMID 34204490, 2021). "PTX-3, CRP, and PCT levels have been investigated to predict the development of inflammation in various cancers, including breast and colon cancer." (PMID 33776564, 2021). "SIR, as evidenced by circulating biomarkers such as the acute-phase protein C-reactive protein (CRP), has consistently been correlated with poor prognosis in many cancer types, including colon cancer." (PMID 34531864, 2021). "Different opinions exist on the relationship between the C-reactive protein-to-albumin ratio (CAR) and the prognosis of colon cancer." (PMID 33299880, 2020). "The PI score is composed of CRP and WBC count and has been validated as a useful predictive factor in lung and colon cancer." (PMID 30367618, 2018). "This study aimed to investigate the relationship between C-reactive protein (CRP) and POD in elderly patients undergoing laparoscopic surgery for colon carcinoma." (PMID 29181397, 2017). "For colon carcinomas, the combination CEA + IL-8 correctly recognized 39 and CEA + CRP 32 of 81 patients correctly as malignant." (PMID 22954206, 2012). "C-reactive protein (CRP), albumin, IL-1α, IL-1β, IL-6, IL-8, IL-10, TNF-α, midkine, VEGF-A, VEGF-C, leptin, adiponectin, and ghrelin serum levels are studied in 126 colon cancer patients and 36 healthy subjects." (PMID 20920199, 2010). "This study aims to evaluate a possible association between the perioperatively induced surgical trauma measured by the CRP concentration in the early postoperative course and long-term oncological outcomes in patients undergoing RAS or LAS for UICC stage I–III colon cancer." (PMID 40383853, 2025). "To the best of our knowledge, we are the first to report that the pretreatment combination of BMI and albumin levels along with CRP levels, which we defined as the NCR in the present study, is an independent indicator of a poor prognosis for patients with primary untreated colon cancer." (PMID 36611408, 2022). "In summary, in the largest study to date and in patients undergoing elective surgery for colon cancer, the anaesthetic approach may affect the magnitude of the postoperative SIR, as evidenced by post-operative CRP concentrations." (PMID 32348308, 2020). "For example, patients with colon cancer have significantly higher CRP concentrations in their blood than the individuals without colon cancer." (PMID 23516433, 2013). "For instance, studies show that the risk of colon cancer is less with a low grade of inflammation, which also shows raised CRP; therefore, various anti-inflammatory drugs may act as a novel therapy to reduce the incidence of colon cancer." (PMID 36381804, 2022). "The modified Glasgow Prognostic Score (mGPS) is a combination of C-reactive protein (CRP) and albumin, reflecting the inflammation and nutritional status of patients, and has an independent prognostic value for patients with various cancers, such as liver, lung, and colon cancer." (PMID 36362488, 2022).
colon carcinoma (continued). "However, the relationship between CRP and POD in patients undergoing laparoscopic surgery for colon carcinoma still remains relatively unknown, which was just the objective of this present study." (PMID 29181397, 2017).